NRAS (NRAS proto-oncogene, GTPase)
Diseases named in the same sentence as NRAS in open-access papers (continued):
Sharing a sentence is not in itself a finding about the gene and the disease.
cancer (continued). "Cancer effects for well-known, frequently mutated genes like NRAS and KRAS in B-ALL were high, which underscores their importance as therapeutic targets." (PMID 38928295, 2024). "RAS genes (KRAS, HRAS, NRAS) are the most frequently mutated oncogene family, with mutations occurring in 19% of patients with cancer." (PMID 38800401, 2024). "In NRAS mutant cancer cells, NOD-like receptor signaling and RHO GTPase-associated pathways were downregulated upon BAY 11-7082 treatment." (PMID 38982514, 2024). "The phenomenon of paradoxical MAPK activation has been extensively investigated in BRAF WT cancer cells, especially in the presence of upstream NRAS mutations." (PMID 38839106, 2024). "Dabrafenib exhibits greater efficacy in suppressing the growth of cancer cell lines with NRAS mutations compared to Vemurafenib (its analogue, PLX-4720), which aligns with our KL relevance ranking." (PMID 39304771, 2024). "The RAS gene family encodes four protein isoforms (KRAS4A, KRAS4B, HRAS, and NRAS), all of which are frequently mutated in various cancer types, including solid tumors and hematological cancers." (PMID 39056802, 2024). "It is the most frequently mutated isoform in human cancers (85%), followed by NRAS (11%) and HRAS (3%)." (PMID 39056802, 2024). "The mislocalization of NRAS was similar for all variants of NRAS tested, indicating that the requirement of GOLGA7 for PM localization of NRASG12D applies to commonly mutated NRAS in cancer." (PMID 38317235, 2024). "Mutations and polymorphisms of the KRAS and NRAS genes have been linked in certain studies to increased cancer aggressiveness, a greater recurrence rate, and a worse response to platinum treatments in patients with LSCC." (PMID 39867023, 2024). "Mutation analysis revealed that RAS mutations, including KRAS and NRAS, were only detected in the tissues of carcinomas." (PMID 39021676, 2024). "RAS genes (KRAS, HRAS and NRAS) comprise the most frequently mutated oncogene family in human cancer." (PMID 37807065, 2023). "Taken together, the fact that we found miR-708 can effectively reduce the metastatic potential of NRAS-mutated cancer suggests a potential therapeutic strategy to treat NRAS mutation-driven tumorigenesis." (PMID 37083947, 2023). "Similar results were obtained when we analyzed the known cancer-associated mutations of the CCR NRas, G12D, G13R, or Q61R33,34." (PMID 37253751, 2023). "Genes in the RAS family (HRAS, KRAS, NRAS) represent the most frequently mutated oncogenes in human cancers, accounting for 3.4 million cancer diagnoses each year." (PMID 37655310, 2023). "Overall, our data suggest that miR-708 can be used as a promising precision medicine for cancers driven by NRAS mutations in the near future." (PMID 37083947, 2023). "Particularly, one of these exons (Ensembl ID: ENSE00001751295.1, exon 3) accumulates mutations in 4052 patients, which accounts for over 60% of the total number of cancer patients with at least one annotated mutation in NRAS." (PMID 37834310, 2023). "According to these findings, the development of DFG-out-type pan-RAF inhibitors holds greater potential for treating patients with cancers carrying oncogenic BRAFV600E or NRAS mutations." (PMID 38111008, 2023). "KRAS, HRAS, and NRAS are the three most commonly mutated RAS isoforms with varying mutation rates in different cancers." (PMID 37662925, 2023). "Compared with the survival plot of patients among all SKCM, LAML, and LUAD, high expression of miR-708 presented a moderately better survival rate in patients with NRAS mutation from three different cancer types, especially in patients with LAML and LUAD." (PMID 37083947, 2023).
cancer (continued). "RAS (HRAS, KRAS, and NRAS), as the second largest mutated gene driver in various human cancers, has long been a vital research target for cancer." (PMID 37704624, 2023). "KRAS, HRAS, and NRAS are oncogenes that are frequently mutated human cancers, with KRAS mutations being the most prevalent, forming 85% of all RAS mutations and affecting about 13% of cancer patients." (PMID 37395796, 2023). "To investigate the prognostic value of miR-708 in NRAS-mutated cancer, we conducted a correlation analysis between miR-708 expression and patient survival with the TCGA database." (PMID 37083947, 2023). "To evaluate the function of miR-708 in different cancers carrying NRAS mutations, we transiently transfected SK-MEL-2, H1299, and THP-1 cells with miR-708 to evaluate the impact of miR-708 on uncontrolled cell proliferation driven by NRAS mutations." (PMID 37083947, 2023). "Here, we report using miRNA-708, which targets the distinct 3’ untranslated region (3’UTR) of NRAS, to develop miRNA-based precision medicine to treat NRAS mutation-driven cancers." (PMID 37083947, 2023). "Collectively, our data unveil the therapeutic potential of using miRNA-708 in NRAS mutation-driven cancers through direct depletion of constitutively active NRAS and thus inhibition of its downstream effectors to decelerate cancer progression." (PMID 37083947, 2023). "RAS (HRAS, KRAS, and NRAS) is the most frequently mutated gene in human cancers, particularly in positions G12 and Q61, and, consequently, the inhibition of oncogenic signaling mediated by RAS has been a key challenge in the field of cancer biology." (PMID 37627277, 2023). "In this work, miR-708 emerges as a novel therapeutic option for NRAS mutation-driven cancer which has long been considered a tough nut to crack in drug design." (PMID 37083947, 2023). "Our findings provide convincing evidence for developing miR-708 as an NRAS-specific targeted therapy and we hope that patients who suffer from cancers driven by NRAS mutation will benefit from our research." (PMID 37083947, 2023). "Overall, it is suggested that using miR-708 to suppress NRAS mutation-driven cancer will be a safe and less toxic approach for standard NRAS-targeted therapy." (PMID 37083947, 2023). "Using targeted sequencing data from MSK-IMPACT and DFCI-GENIE databases we identified co-mutations in HRAS- vs KRAS- and NRAS-mutant cancers." (PMID 37503077, 2023). "Chromosomes 1, 6, and 11 are the nexus of a complex series of copy number changes and rearrangements present in the three cancer cell genotypes, notably involving an early NRAS G12D mutation on 1p." (PMID 37932252, 2023). "Among the RAS protein family, KRAS is the most frequently mutated protein in human cancer, followed by NRAS and HRAS." (PMID 37895906, 2023). "Recent studies have demonstrated that the RAS/MAPK pathway is the most frequently mutated pathway in patients with cancer, with driver mutations in NRAS or KRAS occurring in 40 to 55% of newly diagnosed patients." (PMID 36430761, 2022). "KRAS is the most frequently mutated (85% of all RAS-driven cancers), followed by NRAS (12%) and HRAS (3%) (COSMIC v80)." (PMID 35456940, 2022). "This strategy should be more effective (multi-pathway inhibition) in a greater proportion of patients (BRAF or NRAS mutated) than existing targeted therapies, and should minimize the development of cancer cell resistance." (PMID 35158973, 2022). "RAS is the most frequently mutated oncogene in cancer, and it includes KRAS, HRAS, and NRAS subtypes of which KRAS is commonly seen in cancer." (PMID 35685832, 2022). "The oncogenic Ras isoforms, KRas, HRas and NRas, whose mutations have been found in more than 30% of human cancers, as well as overexpression of growth factors and mutations of their receptors in human cancer, all lead to the activation of this pathway." (PMID 35563547, 2022).
cancer (continued). "NRAS, a protein mutated in several cancer types, is involved in key drug resistance mechanisms and is an intractable target." (PMID 35534592, 2022). "The mutational analysis determined that genes previously identified in cancers were most commonly observed in the profiled patients with mutations in NRAS, KRAS, JAK2, and CREBBP." (PMID 36497424, 2022). "KRAS is the most frequently mutated isoform among the RAS family of genes and is associated with an overall percentage of 75–83% of all RAS-mutated cancers, whereas NRAS is detected in only 8–17% and HRAS in 3–7% of all cases." (PMID 36359850, 2022). "Clear examples are missense mutations in classic RAS genes (KRAS, HRAS and NRAS) that underlie the development of approximately 13% of human cancers." (PMID 35120522, 2022). "The three RAS oncogenes (HRAS, KRAS and NRAS) are part of the most frequently mutated gene family in human cancer, since over 20% of human cancers harbor mutations in one of the three RAS genes, making them the most prevalent oncogenic drivers." (PMID 35456940, 2022). "Dependency on SHOC2 was particularly evident in cancer cell lines with certain H/K/NRAS hotspot mutations (G13/Q61), indicating that SHOC2–PP1C complex formation with these mutated RAS isoforms is a likely driver of cell growth." (PMID 35768504, 2022). "In conclusion, JNK inhibitor co-treatment can enhance the cancer cytotoxic effect of ferroptosis inducers in NRAS and KRAS mutation-harboring cells (HT-1080 and MIA PaCa-2)." (PMID 36232313, 2022). "Mutations in one of the three RAS genes (HRAS, KRAS, and NRAS) are present in nearly 20% of all human cancers." (PMID 36334633, 2022). "To address the NRAS mutation profile, we retrieved the NRAS mutation data from pediatric Cancer Genome Project (PCGP) and identified a very similar pattern between our study cohort and PCGP study cohort." (PMID 35211470, 2022). "The top four mutated genes in pediatric cancers were NRAS (1.8%), KRAS (0.9%), JAK2 (0.3%), and CREBBP (0.3%), highlighting that these genes should be analyzed further to assess the clinical significance of these mutations." (PMID 36497424, 2022). "Similar rebound signaling occurs after MEK inhibitor treatment in HRAS- and NRAS-mutated cancer cells." (PMID 33924994, 2021). "The RAS oncogenes (KRAS, HRAS, and NRAS) are frequently mutated in human cancers, with KRAS being the most commonly affected." (PMID 34947990, 2021). "The major representatives of the RAS gene family, namely HRAS, KRAS and NRAS, are the most frequently mutated genes in malignant neoplasms, and have been under the spotlight of scientific research for the development of targeted therapies." (PMID 34948093, 2021). "Here, we show that LT, through inhibiting MEK1/2-ERK activation, inhibits the proliferation of cancer cells with NRAS/BRAF mutations." (PMID 34064422, 2021). "RAS genes (HRAS, KRAS, and NRAS) comprise the most frequently mutated oncogene family in human cancer." (PMID 34298594, 2021). "RAS genes (HRAS, KRAS, and NRAS) are the most frequently mutated genes in cancer cells, showing a mutation frequency of 30% in all cancer cells." (PMID 34830024, 2021). "The three isoforms of Ras oncoproteins, HRAS, KRAS, and NRAS, are frequently mutated in a variety of human cancers." (PMID 33580066, 2021). "Mutations in well-known cancer genes located on chromosome 1p, such as NRAS (1p13.2), GADD45A (1p31.2–31.1), CDKN2C (1p32.2), RAD45(1p32) and EPB41 (1p36.2–p34), have so far only sporadically been detected." (PMID 34385566, 2021). "Reported data indicate that cancer cells harboring FGFR1 amplifications can acquire resistance to FGFR inhibitors mediated by overexpression of NRAS, MET amplification, mutational inactivation of PETN, and activation of AKT." (PMID 34114373, 2021).
cancer (continued). "Knocking down PIP5K1A expression specifically reduced the viability of KRAS transformed cells versus NRAS or HRAS mutated cancer cells and had an additive effect with MEK inhibitors in KRAS mutant pancreatic cancer cell models." (PMID 33562401, 2021). "CircPVT1 knockdown significantly reduced NRAS levels and attenuated cancer hallmark phenotypes such as proliferation, migration, resistance to apoptosis, cytoskeletal disorganization, and epithelial-mesenchymal transition." (PMID 33907219, 2021). "Inhibition of the RAF-MEK1/2-ERK signaling pathway is an ideal strategy for treating cancers with NRAS or BRAF mutations." (PMID 34064422, 2021). "HRAS and NRAS mutations are common in other cancer types including head and neck, skin, and hematopoietic cancers." (PMID 33924994, 2021). "The RAS family (KRAS, HRAS, NRAS), are frequently mutated in human cancer, approximately 25% of human malignances harbor RAS mutations." (PMID 32269211, 2020). "For example, NRAS mutations at codons 12, 13, and 61 were characterized as driver mutations in many cancers." (PMID 31925297, 2020). "Analysis of the same database for DDR1 expression vs. NRAS mutational status showed DDR1 to be slightly downregulated in all NRAS-mutated cancers (effect size −0.26, p = 0.00053) and with a similar tendency (effect size −0.29, p = 0.065)." (PMID 33014862, 2020). "Specifically, poorer survival was associated with samples that had a SPRED1 aberration in combination with another cancer driver mutation: NRAS, NF1 or KIT (log-rank test, p = 0.0074)." (PMID 33067454, 2020). "Three cellular Ras genes encode the four members of the RAS family of small GTPases, KRAS4A, KRAS4B, HRAS, and NRAS, whose mutations drive one-third of human cancers." (PMID 31941155, 2020). "Mutations within the Ras family are not evently distributed, with KRas mutations found in 85% of these cancers, followed by NRas (11%) and HRas (4%)." (PMID 32456244, 2020). "We therefore estimated the cancer cell content of biopsy samples using Sanger sequencing to detect the likely truncal KRAS/NRAS mutations identified previously by clinical sequencing assays." (PMID 33014822, 2020). "NRas mutations are prominant in skin (<25%) and hematological (<15%) cancers and HRas mutations often exist in head and neck cancers." (PMID 32456244, 2020). "RAS subfamily comprises the ubiquitously expressed human RAS proteins KRAS4A, KRAS4B (the two KRAS splice variants), HRAS, and NRAS, which are frequently mutated in cancer." (PMID 31681616, 2019). "The RAS family of proto-oncogenes comprises HRAS, KRAS, and NRAS, which are among the most mutated genes in human cancers." (PMID 31852884, 2019). "RAS family genes, including HRAS, KRAS and NRAS, are the most common oncogenes in human cancer, and encode extremely similar proteins made up of chains of 188 to 189 amino acids." (PMID 30971271, 2019). "The members of the RAS subfamily of GTPases, which includes KRAS, HRAS, and NRAS, are frequently mutated in cancer." (PMID 31681616, 2019). "These decreases were observed in both BRAF- and NRAS-mutated arms, and were moderate and consistent with observations in other cancer studies with MEK inhibitors, such as the observed suppression of pERK by cobimetinib (GDC-0973) both in vitro and in vivo." (PMID 30956763, 2019). "Although oncogenic mutations in the three major Ras isoforms, KRAS, HRAS and NRAS, are present in nearly a third of human cancers, therapeutic targeting of Ras remains a challenge due to its structure and complex regulation." (PMID 31497244, 2019). "Of these, KRAS is the most mutated (86% of all RAS-mutant cancers), followed by NRAS (12%), and HRAS (4%)." (PMID 31681587, 2019).
cancer (continued). "These include KRAS, HRAS and NRAS and a variety of different mutations that mirror those found in human cancers with the major RAS effectors such as CRAF, PI3K and RALGDS." (PMID 29989546, 2018). "The three canonical Ras proteins (KRas, NRas, and HRas) are mutated in a broad range of human cancers with KRAS, NRAS, and HRAS mutations accounting for ∼22, ∼8, and ∼3% of all cancers, respectively." (PMID 29282294, 2018). "KRAS is mutated in nearly a quarter of a wide spectrum of cancers, NRAS is mutated in <10% of cancers, but at a high frequency in specific cancers, while HRAS is rarely mutated in any cancer." (PMID 30194290, 2018). "A known major activator of ERK phosphorylation in cancer is oncogenic NRAS and we show that knockdown of NRAS in cells, which bear a Q61 NRAS mutation, sensitises to ER-stress." (PMID 29329780, 2018). "These mutants were used at the positions Q61 and G12, for NRAS and HRAS respectively, as these are the positions most frequently mutated in human cancer involving NRAS and HRAS mutants." (PMID 29989546, 2018). "We conclude that oncogenic RAC1 and NRAS mutations protect cancer cells from ER-stress by activating ERK1/2." (PMID 29329780, 2018). "The thorough analysis of the few cases with membrane staining (n = 12) revealed that all but one carcinoma were wild type for the studied mutations (NRAS, BRAF or TERTp)." (PMID 29298843, 2018). "We show that NRAS‐mutated cancer cells exhibit predilection for the lungs via expression of chemokine ligands and not receptors." (PMID 28341702, 2017). "The RAS gene family members include HRAS, KRAS, and NRAS, with the latter two being the isoforms commonly mutated in cancers." (PMID 27650277, 2017). "One case (HGCA4) harbored an NRAS hotspot mutation p.Q61H, which has been reported in many cancers, including thyroid, lung, skin and CRC." (PMID 28179590, 2017). "TAK-632 was initially described to have cellular activity against mutated BRAF or mutated NRAS cancer cell lines and antitumor efficacy in vivo in BRAF and NRAS mutated xenograft models." (PMID 28002790, 2017). "We also show that NRAS mutations are associated with overexpression of the oncogene in accord with human cancer data and that overexpression of NRASWT also suffices for lung metastasis." (PMID 28341702, 2017). "Overall, we observed an increased frequency in the rate of NRAS mutations, especially at Q61, when compared to other cancers." (PMID 28427158, 2017). "We used an array of mouse model systems to identify that NRAS mutations or gain predisposes cancer cells to spontaneously colonizing the lungs." (PMID 28341702, 2017). "Through extensive sequencing on 50 cancer-related genes, a novel germline mutation on oncogene NRAS, instead of on well-known cancer-predisposing genes, was observed in our population." (PMID 27121310, 2016). "We first illustrated the effect of individual hotspot mutations in BRAF, KRAS and NRAS on the sensitivity of cancer cells treated by MEK inhibitors (PD-0325901 and AZD6244)." (PMID 27356755, 2016). "In particular, activating mutations at codon 61 occur more frequently than at codon 12 of HRAS and NRAS in most cancer types, in contrast to KRAS where a mutation at codon 12 is predominant." (PMID 26799184, 2016). "The RAS genes, KRAS, HRAS, and NRAS, are the most frequently mutated proto-oncogenes in human cancers in the United States and are responsible for 43% of all cancer deaths." (PMID 27684555, 2016).